ARRB1 (arrestin beta 1)
Diseases named in the same sentence as ARRB1 in open-access papers (continued):
Sharing a sentence is not in itself a finding about the gene and the disease.
Stroke (2 papers, 2015 to 2019). Sudden impairment of blood flow to a part of the brain due to occlusion or rupture of an artery to the brain. "Finally, the potential of rTMS in promoting neuroprotection and plasticity in stroke is further corroborated by the results that showed a significant increase in expression of genes involved in GPCR signaling (Arrb1, Adcy8 and Bdnf)." (PMID 26431529, 2015).
triple-negative breast carcinoma (2 papers, 2020 to 2022). An invasive breast carcinoma which is negative for expression of estrogen receptor (ER), progesterone receptor (PR), and human epidermal growth factor receptor 2 (HER2). "In triple-negative breast cancer, miR-374a is upregulated relative to levels in non-tumor tissues and promotes cell proliferation, migration, and tumor progression in vivo by targeting arrestin-β1 (ARRB1)." (PMID 32674274, 2020).
acute lymphoblastic leukemia (1 paper, 2020). Leukemia with an acute onset, characterized by the presence of lymphoblasts in the bone marrow and the peripheral blood. "ARRB1 also regulates self-renewal in the cancer stem cell population in B-lineage acute lymphoblastic leukemia (B-ALL), which predominantly affects B cells and approximately accounts for 70% of childhood acute lymphoblastic leukemia (ALL) cases." (PMID 33297302, 2020).
acute pancreatitis (1 paper, 2021). An acute inflammatory process that leads to necrosis of the pancreatic parenchyma. "Preceding research from our team revealed that ARRB1 alleviated acute pancreatitis via repression of NF-κBp65 activation." (PMID 34455423, 2021).
AIDS (1 paper, 2022). A syndrome resulting from the acquired deficiency of cellular immunity caused by the human immunodeficiency virus (HIV). "We screened four immune cell-related genes, ARRB1, DPEP2, LTBP3, and RGCC, which may be considered as the diagnostic markers for HIV-1/AIDS." (PMID 36123690, 2022).
Alzheimer disease (1 paper, 2022). A progressive, neurodegenerative disease characterized by loss of function and death of nerve cells in several areas of the brain leading to loss of cognitive function such as memory and language. "For example, apoptosis of neurons during Alzheimer's disease progression could be induced by PGD2 which stimulated expression of BIK and suppressed expression of ARRB1." (PMID 33683530, 2022).
Anxiety (1 paper, 2023). Intense feelings of nervousness, tension, or panic often arise in response to interpersonal stresses. "While our results cannot be translated directly to humans, it is interesting that Arrb1 upregulation was observed in both male and female low anxiety, High Activity mice." (PMID 36514243, 2023).
bone tumour (1 paper, 2022). "It has been demonstrated that hydroxyapatite-CU systems may kill bone tumour cells in a dose-dependent manner by inducing apoptosis, raising AMPK and ARRB1 levels, and causing a G2/M cell cycle." (PMID 36079777, 2022).
brain tumors (1 paper, 2021). "In keeping with the documented organ and site dependency of its over‐ and under‐expression, ARRB1 appears to play a tumor‐suppressor role in brain tumors." (PMID 32920979, 2021). "Notably, under‐expression of ARRB1 has been documented in brain tumors." (PMID 32920979, 2021).
Cholecystitis (1 paper, 2021). The presence of inflammatory changes in the gallbladder. "Among the 62 GBC tissue samples, 43.55% (27/62) of cases were strong stained, 22.58% (14/62) of cases were medium stained, 33.87% (21/62) of cases were weak or negatively stained, the opposite of that only 6.67% (2/30) of the cholecystitis tissues showed strong staining of ARRB1 protein." (PMID 33753990, 2021). "The western blot data showed that the protein level of ARRB1 was obviously upregulated in GBC tissues compared with the nontumor counterparts and cholecystitis tissues." (PMID 33753990, 2021).
cholelithiasis (1 paper, 2021). The presence of crystallized deposits forming in the gallbladder or biliary tree, primarily composed of cholesterol, bilirubin, and bile. "Assessed with immunohistochemical staining, the expression of ARRB1 tended to be higher in GBC tissues than that in cholelithiasis specimens, and ARRB1 immunoreactivity was mainly observed in the cytoplasm of tumor cells." (PMID 33753990, 2021).
COVID-19 (1 paper, 2024). A disease caused by infection with severe acute respiratory syndrome coronavirus 2. "ARRB1 exhibited significant upregulation in the COVID-19 and PQ comparison groups." (PMID 39301288, 2024).
enamel hypoplasia (1 paper, 2021). "JNK3 and Arrb1 might be used as biomarkers for diagnosis or therapeutic targets for the treatment of enamel hypoplasia, which is possible in the future." (PMID 35004671, 2021).
Epstein-Barr virus infection (1 paper, 2021). An infection that is caused by Epstein-Barr virus. "Similarly, ARRB1 protein was decreased after Epstein-Barr virus-infection in mice." (PMID 33633136, 2021).
HCMV infection (1 paper, 2017). "Network analysis of the differentially expressed genes in cord DCs, revealed among the downregulated genes after 16 h of HCMV infection several GPCRs with pro-inflammatory response function (ADORA3, ARRB1, C5AR1, CXCR4, GPR34, GPR183, GRK3, and RGS18)." (PMID 28993767, 2017).
head and neck cancer (1 paper, 2020). A primary or metastatic malignant neoplasm affecting the head and neck. "Specifically, for head and neck cancer, the expression levels of three genes, NFE2L2, RMND5A and SLC44A1, were associated with increased smoking-related mutational signature, while an inverse association was observed for one gene, ARRB1." (PMID 32928150, 2020).
HIV-1 infection (1 paper, 2022). The type species of lentivirus and the etiologic agent of acquired immunodeficiency syndrome (AIDS). "As the best model for diagnosing HIV-1±, RF was used to select four critical immune cell-related genes, namely, ARRB1, DPEP2, LTBP3, and RGCC, and a nomogram model was created to predict the occurrence of HIV-1 infection based on four key immune cell-related genes." (PMID 36123690, 2022). "These genes, including ARRB1 and RGCC, were shown to be involved in the regulation of immune-related biological processes, which is consistent with the classical process required for HIV-1+, suggesting a potential mechanism of HIV-1 infection." (PMID 36123690, 2022).
hydrops (1 paper, 2026). "At E15.5, Arrb1/2ΔiLEC embryos exhibited profound hydrops fetalis and increased embryonic mortality compared with control Arrb1/2fl/fl embryos." (PMID 41885968, 2026).
lung fibrosis (1 paper, 2024). "When challenged with bleomycin, mice with lung fibroblast-specific deficiency of Arrb1 showed to a decrease in hydroxyproline content in the lungs compared to littermate control mice, and reduced lung fibrosis was confirmed with Trichrome staining." (PMID 38736470, 2024). "We used conventional deletion as well as cell type-specific deletion of ARRB1 in mice and found that Arrb1 deficiency in fibroblasts protects mice from lung fibrosis, and the knockout mice exhibit enhanced AEC2 regeneration in vivo, suggesting a role of fibroblast-derived ARRB1 in AEC2 renewal." (PMID 38736470, 2024). "Our data show that mice with Arrb1 deficiency in fibroblasts were protected from bleomycin-induced lung fibrosis, Arrb1-deficient fibroblasts promoted AEC2 proliferation, and Arrb1 deficiency in fibroblasts led to decreased Ccl7 expression." (PMID 38736470, 2024). "We investigated the role of ARRB1 in regulating AEC2 regeneration using conventional deletion as well as cell type-specific deletion of ARRB1 in mice with a lung fibrosis mouse model." (PMID 38736470, 2024). "In this study, we investigated the role of ARRB1 in AEC2 renewal and in lung fibrosis and found that Arrb1 deficiency in fibroblasts enhanced AEC2 regeneration and protected mice from lung fibrosis." (PMID 38736470, 2024). "We found that targeted deletion of ARRB1 in fibroblasts promoted AEC2 regeneration and ameliorated lung fibrosis." (PMID 38736470, 2024). "In this study, we investigated the role and mechanism of Arrestin beta 1 (ARRB1) in AEC2 renewal and in lung fibrosis." (PMID 38736470, 2024). "In this study, we investigated the role of Arrestin beta 1 (ARRB1) in AEC2 renewal and in lung fibrosis." (PMID 38736470, 2024).
medulloblastoma (1 paper, 2020). A malignant, invasive embryonal neoplasm arising from the cerebellum. "ARRB1 predominantly functions as an oncogene that positively regulates self-renewal in CSCs with the exception of medulloblastoma CSCs where ARRB1 inhibits SHH/Gli signaling and expression of target genes associated with stemness." (PMID 33297302, 2020). "Similarly, ARRB1 overexpression in SHH-medulloblastoma CSCs resulted in decreased Gli1 protein levels." (PMID 33297302, 2020). "Taken together, miR-326 and its host protein, ARRB1, function together to negatively regulate SHH/Gli signaling in medulloblastoma CSCs in a complementary manner." (PMID 33297302, 2020). "Interestingly, ARRB1 and its intragenic miR-326 (located within ARRB1 gene) are down-regulated in SHH medulloblastoma derived CSCs." (PMID 33297302, 2020).
melanoma (1 paper, 2022). A malignant, usually aggressive tumor composed of atypical, neoplastic melanocytes. "Finally, ARRB1 expression was significantly associated with MSI, PD-L1, and TMB in some tumors and with the efficacy of immune checkpoint inhibitors (ICIs) in melanoma." (PMID 36213111, 2022). "This suggests the potential of ARRB1 to predict the efficacy of anti-PD1 therapy in melanoma." (PMID 36213111, 2022).
metastatic melanoma (1 paper, 2022). A melanoma that has spread from its primary site to another anatomic site. "Although there were no positive results in the renal cell carcinoma and advanced uroepithelial carcinoma cohorts, we found significantly low expression of ARRB1 in the responder group in the metastatic melanoma anti-PD1 therapy cohort." (PMID 36213111, 2022).
multiple myeloma (1 paper, 2025). "While ARRB1 has been implicated in cancer progression, its role in modulating host immunity against multiple myeloma (MM) remains unexplored." (PMID 41373634, 2025). "Second, the dramatic reduction in PD-1 expression we observed suggests that ARRB1 inhibition could enhance the efficacy of PD-1/PD-L1 checkpoint inhibitors, which have shown limited success in multiple myeloma as monotherapy." (PMID 41373634, 2025).
myeloma (1 paper, 2025). "Here, we demonstrate that host ARRB1 deficiency significantly enhances anti-myeloma immunity and prolongs survival in a syngeneic murine MM model." (PMID 41373634, 2025). "Using Vk*MYC myeloma cells transplanted into wild-type and ARRB1 knockout mice, we show that ARRB1 deficiency in the host microenvironment promotes robust T cell infiltration and activation while reducing immunosuppressive myeloid populations." (PMID 41373634, 2025). "This preservation of splenic architecture and significantly lower CD138+ myeloma cells in ARRB1-deficient hosts suggests reduced tumor burden and/or altered immune cell trafficking, consistent with enhanced anti-tumor immunity." (PMID 41373634, 2025). "To determine whether host ARRB1 deficiency alters myeloma-induced bone destruction, we performed microCT analysis of distal femurs from wild-type (WT) and ARRB1 knockout (KO) mice." (PMID 41373634, 2025). "Furthermore, ARRB1 deficiency conferred protection against myeloma-induced bone disease, suggesting a dual role in immune regulation and bone homeostasis." (PMID 41373634, 2025). "This dramatic improvement in survival suggests that host ARRB1 plays a critical role in conferring anti-myeloma immunity." (PMID 41373634, 2025). "In summary, we identify host ARRB1 as a critical negative regulator of anti-myeloma immunity that promotes immune exhaustion and limits survival." (PMID 41373634, 2025). "In this study, we investigated the role of host ARRB1 in anti-myeloma immunity using a well-established syngeneic murine model." (PMID 41373634, 2025). "To investigate the role of host ARRB1 in anti-myeloma immunity, we utilized the well-characterized Vk*MYC syngeneic mouse model." (PMID 41373634, 2025). "From a therapeutic perspective, our findings identify ARRB1 as an attractive target for enhancing anti-myeloma immunity." (PMID 41373634, 2025). "Our study reveals a previously unrecognized role for host ARRB1 as a critical negative regulator of anti-myeloma immunity." (PMID 41373634, 2025). "The protection against myeloma-induced bone disease in ARRB1 knockout mice reveals an unexpected connection between immune regulation and bone homeostasis." (PMID 41373634, 2025). "None of the ARRB1 knockout (KO) recipient mice had detectable M-protein, indicating resistance to myeloma development in ARRB1-deficient mice." (PMID 41373634, 2025). "Additionally, CD138+ myeloma cells in spleen and bone marrow were reduced by 17-fold and 3-fold, respectively, in ARRB1 knockout mice." (PMID 41373634, 2025).
neuroblastoma (1 paper, 2017). Neuroblastoma (NB) is the most common solid, extracranial childhood tumor. "In this study, we found that ARRB1 and ARRB2 were low in the serum of AD patients, and ARRB1 is important in Aβ25-35-mediated transient activation of autophagy in human neuroblastoma SH-SY5Y cells." (PMID 28611418, 2017).
nicotine dependence (1 paper, 2022). Physical and psychological dependence on nicotine. "In a European cohort, a haplotype constructed from 6 SNPs within ARRB1 was significantly associated with nicotine dependence." (PMID 36386175, 2022).
nonalcoholic fatty liver disease (1 paper, 2021). "Synchronously, ARRB1 also mediated the development of nonalcoholic fatty liver disease through TRAFs, which is another important member of TNF-α pathway." (PMID 33753990, 2021).
tauopathy (1 paper, 2022). Neurodegenerative disorders involving deposition of abnormal tau protein isoforms (tau proteins) in neurons and glial cells in the brain. "In vivo, genetic reduction of ARRB1 not only alleviated tauopathy in PS19 transgenic mice but also functionally rescued the prominent deficits in synaptic plasticity (i.e., PPF and LTP) and synaptic integrity in PS19 acute slices and neurons." (PMID 34862271, 2022).
tumor (40 papers, 2012 to 2025). "Our observation that ARRB1 deficiency promotes T cell expansion while reducing MDSC accumulation reveals a dual mechanism for enhanced anti-tumor immunity." (PMID 41373634, 2025). "This reciprocal relationship between effector T cells and suppressive myeloid populations suggests that ARRB1 deficiency shifts the immune balance toward anti-tumor immunity." (PMID 41373634, 2025). "Quantitative analysis revealed that compared to wild-type, ARRB1-deficient hosts maintained higher trabecular bone volume fraction (BV/TV) despite tumor challenge." (PMID 41373634, 2025). "The possible effect of ARRB1 on tumor development is still controversial, and ARRB1 is associated with the prognosis of patients with tumors in a variety of cancers." (PMID 36245844, 2022). "In conclusion, this study provides valuable insights into the role of ARRB1 in cancer and provides a theoretical basis for investigating the potential mechanisms underlying the relevance of ARRB1 expression to tumor prognosis and immune regulation." (PMID 36213111, 2022). "The more complex tumor‐promoting effects of ARRB1 loss are related to the protein's importance for inducing E2F1 acetylation, a modification that ultimately leads to the transcriptional activation of E2F1's pro‐apoptotic target genes." (PMID 32920979, 2021). "Additionally, ARRB1 has been implicated in tumor vascularization, metastasis and metabolic reprogramming." (PMID 40486495, 2025). "Our results suggest that enhanced anti-tumor immunity in ARRB1-deficient hosts may indirectly protect against bone destruction by reducing tumor burden." (PMID 41373634, 2025). "ARRB1 deficiency enhances T cell responses, reduces immunosuppressive myeloid populations, and decreases PD-1 expression, creating an immune microenvironment that is hostile to tumor growth." (PMID 41373634, 2025). "Our findings reveal that ARRB1 deficiency in the host microenvironment dramatically enhances anti-tumor immunity through multiple mechanisms, including increased T cell infiltration and activation, reduced MDSC accumulation, and decreased expression of the exhaustion marker PD-1." (PMID 41373634, 2025). "Furthermore, ARRB1 is widely associated with indicators related to the tumor immune microenvironment in a variety of cancers and may be an important factor influencing or predicting the efficacy of immunotherapy." (PMID 36213111, 2022). "Furthermore, putative correlations between ARRB1 and tumor-infiltrating immune cells, the signatures of T-cell subtypes, immunomodulators, the tumor mutation burden (TMB), Programmed cell death ligand 1 (PD-L1), and microsatellite instability (MSI) were also explored." (PMID 36213111, 2022). "ARRB1 was initially known as a multifunctional adaptor protein and is currently recognized for its involvement in tumor malignancy and immune responses." (PMID 40486495, 2025). "Similar patterns were observed in the peripheral blood, where PD-1 expression was markedly decreased in T cells and MDSCs in ARRB1 knockout mice after tumor implantation." (PMID 41373634, 2025). "Extensive research has indicated that β-arrestin 1 (ARRB1) plays a significant role in tumor malignancy." (PMID 40486495, 2025). "Functional analysis confirmed that ARRB1 and CTBP1/2 were associated with early tumor development, while COL1A2 and CEBPZ were involved in extracellular matrix remodeling and transcriptional regulation, respectively." (PMID 40362431, 2025). "We observed significant differences in splenic morphology between wild-type littermates and ARRB1 knockout tumor-bearing mice." (PMID 41373634, 2025). "To determine the immunological basis for tumor resistance and improved survival in ARRB1 knockout mice, we analyzed immune cell populations at 28 days post-tumor injection." (PMID 41373634, 2025).